SERPINF1 (serpin family F member 1)
Diseases named in the same sentence as SERPINF1 in open-access papers (continued):
Sharing a sentence is not in itself a finding about the gene and the disease.
glioma (continued). "In the present study, we found that high expression of SERPINF1 correlated with risk factors of glioma, such as wild-type IDH, 1p19q non-codeletion, and a higher WHO grade." (PMID 36980858, 2023). "Overall, our results suggest that SERPINF1 may be a candidate prognostic predictor and potential therapeutic target for glioma." (PMID 36980858, 2023). "The effects of SERPINF1 knockdown on glioma cells and GSCs were also evaluated in vitro." (PMID 36980858, 2023). "In vitro experiments confirmed that SERPINF1 knockdown could suppress the proliferation, invasion, and migration of glioma cells." (PMID 36980858, 2023). "Compared to lower-grade gliomas (LGGs), glioblastomas (GBMs) expressed higher levels of SERPINF1." (PMID 36980858, 2023). "High SERPINF1 expression portends a poor prognosis in glioma patients." (PMID 36980858, 2023). "Furthermore, the relationship between SERPINF1 expression and glioma stemness was explored in vitro." (PMID 36980858, 2023). "Additionally, we analyzed the relationship between SERPINF1 expression and tumor stemness in glioma." (PMID 36980858, 2023). "In addition, SERPINF1 expression was significantly upregulated in glioma stem cells (GSCs) compared to parental glioma cells." (PMID 36980858, 2023). "Furthermore, glioma patients with high SERPINF1 expression experienced poorer survival than those with low SERPINF1 expression." (PMID 36980858, 2023). "Moreover, the single-cell analysis showed that the Notch signaling pathway was substantially enriched in glioma cells with high SERPINF1 expression." (PMID 36980858, 2023). "SERPINF1 silencing may perturb the transformation of glioma cells into GSCs, indicating that SERPINF1 is a potential target for glioma stemness." (PMID 36980858, 2023). "Given the essential role of SERPINF1 in glioma, we performed SCENIC analysis to infer the potential TFs that may modulate the expression of SERPINF1." (PMID 36980858, 2023). "Besides, SERPINF1 knockdown could suppress the proliferation, invasion, and migration of glioma cells in vitro." (PMID 36980858, 2023). "Therefore, SERPINF1-related Notch signaling activation may contribute to stemness maintenance in glioma." (PMID 36980858, 2023). "Finally, the effects of SERPINF1 knockdown on glioma cells and GSCs were evaluated in vitro." (PMID 36980858, 2023). "Therefore, the relationship between SERPINF1 expression and glioma stemness was investigated." (PMID 36980858, 2023). "Furthermore, STAT1, CREM, and NR2F2 may participate in the transcriptional regulation of SERPINF1 in glioma." (PMID 36980858, 2023). "In addition, ROC curve analysis showed that SERPINF1 expression could predict the 3-, 5-, and 8-year survival rates of glioma patients with high AUC, suggesting SERPINF1 has huge prospects as a novel prognostic predictor for glioma." (PMID 36980858, 2023). "Additionally, ROC curve analysis demonstrated that SERPINF1 expression could effectively predict the 3-, 5-, and 8-year survival of glioma patients in all three datasets." (PMID 36980858, 2023). "In addition, SERPINF1 is expected to be a stem cell marker in glioma." (PMID 36980858, 2023). "Serpin family F member 1 (SERPINF1) reportedly plays multiple roles in various tumors; however, its clinical significance and molecular functions in glioma have been largely understudied." (PMID 36980858, 2023). "The expression features and prognostic value of SERPINF1 in glioma have hitherto not been comprehensively documented in the literature." (PMID 36980858, 2023). "The expression of SERPINF1 is significantly upregulated in GSCs, and SERPINF1 knockdown impairs the sphere formation of GSC-A172 and GSC-LN18, indicating that SERPINF1 is a potential target for glioma stemness." (PMID 36980858, 2023).
glioma (continued). "Our data indicated that the Wnt pathway activation related genes such as CCN4, FOSL1, LGR6, MMP7, RAC2, SERPINF1 and TCF7 were upregulated, while Wnt pathway inactivation related gene such as CXXC4 was downregulated in radiotherapy treated glioma patients from TCGA database." (PMID 34852024, 2021). "Up-regulation of SERPINF1/Serpinf1 by corticosteriod analogues has been reported in a variety of cell types: HUVECs, primary human trabecular meshwork cells, human ARPE-19 cells, mouse 3T3-L1 cells, mouse Müller glial cells and rat glioma cells." (PMID 25881671, 2015). "However, the functional role of SERPINF1 in glioma has not been elucidated in detail." (PMID 36980858, 2023).
pancreatic cancer (17 papers, 2009 to 2025). "SERPINF1, previously known as pigment epithelium-derived factor, PEDF, is a potent anti-angiogenic factor and more than half of pancreatic cancers have reduced levels of SERPINF1." (PMID 34503201, 2021). "In addition, studies have reported increased concentrations of C3, AHSG, and SERPINF1 proteins in the peripheral blood of pancreatic cancer patients." (PMID 37759310, 2023). "SERPINF1 inhibits tumor angiogenesis and metastasis, induces apoptosis and differentiation of tumor cells, and has antitumor effects in a variety of cancers including cervical and pancreatic cancers." (PMID 37872487, 2023). "In turn, common regions of LOH also included two genes that have been involved in pancreatic cancer: the RPH3AL and SERPINF1 genes at chromosome 17p13." (PMID 21811587, 2011).
lung carcinoma (15 papers, 2009 to 2025). "For example, lower levels of SerpinF1 and C6 were detected in lung cancer tissues than uninvolved normal lung tissues, but higher levels were observed in normal lung tissues collected a shorter distance from tumours." (PMID 30841875, 2019). "SHROOM3 and SERPINF1 play a role in kidney transplantation and chronic kidney disease, while RCN3 and NTM are potential prognostic molecules for non‐small cell lung cancer and ovarian cancer, but they have not been explored in kidney tumors." (PMID 37676078, 2023).
retinoblastoma (15 papers, 2010 to 2023). A malignant tumor that originates in the nuclear layer of the retina. "Moreover, researchers investigated patients with retinoblastoma and found that pathological cells in their body rely on SERPINF1, with its contribution to neuron differentiation." (PMID 32595417, 2020).
atherosclerosis (13 papers, 2013 to 2025). A disease characterized by the build-up of fatty material and calcium deposition in the arterial wall resulting in partial or complete occlusion of the arterial lumen. "Previous studies had reported that PEDF encoded by SERPINF1 gene was a biomarker of atherosclerosis." (PMID 37089432, 2023). "According to our study, Serpinf1 was highly expressed in fibroblasts and fibromyocytes, and previous research also depicted that these cells had the important role in atherosclerosis." (PMID 37089432, 2023). "The results revealed the fact that Serpinf1 experienced a significantly diminishing expression (p = 1.688e-191, likelihood ratio tests) with the progression of atherosclerosis." (PMID 37089432, 2023). "We proposed a potential mechanism, SERPINF1 regulated the development of atherosclerosis and plaques stability through Jak-STAT signaling pathway." (PMID 37089432, 2023). "With more and more literature suggesting that fibroblasts play the important role in atherosclerosis, our finding will reveal a potential mechanism of SERPINF1 in the atherosclerosis." (PMID 37089432, 2023). "We found that SERPINF1, which was highly expressed in fibroblasts, participated in the regulation of atherosclerosis through various signaling pathways." (PMID 37089432, 2023). "Thus, we proposed that SERPINF1, which was abundantly expressed in fibroblasts, involved in the pathological process of atherosclerosis through preventing the activation of Jak-STAT signaling." (PMID 37089432, 2023). "Meanwhile, Serpinf1 were also found to be expressed in fibroblasts of additional mice atherosclerotic single-cell RNA-seq data analysis, and was highly expressed at 8 and 22-weeks of atherosclerosis." (PMID 37089432, 2023). "We speculated that the downregulation of Serpinf1 might be a possible reason for the intensification of atherosclerosis." (PMID 37089432, 2023). "On the one hand, the downregulation of SERPINF1 reduced the inhibition of Jak-STAT signaling, causing vascular remodeling, thereby compensating for the early endothelial injury and accelerating the progression of atherosclerosis." (PMID 37089432, 2023). "Interestingly, out of these, SERPINA1, SERPINE1, and SERPINF1 are known to positively correlate with atherosclerosis in humans." (PMID 35440683, 2022). "We speculated that SERPINF1 played the complicated role in preventing atherosclerosis." (PMID 37089432, 2023). "In addition, cluster 0 expressed Serpinf1, involved in ossification and osteoblast differentiation, Hsd11b1, shown to exacerbate atherosclerosis, Pex5l, expressed in macrophages and Gfra2 in monocytes, as well as cystatin C, associated with coronary artery calcification." (PMID 35163719, 2022). "Although the role of SERPINF1 gene in atherosclerosis had not been reported yet, the pigment epithelium-derived factor (PEDF) encoded by SERPINF1 gene had been widely reported in preventing atherosclerosis." (PMID 37089432, 2023). "So far, no study had reported that SERPINF1 was involved in the regulation of atherosclerosis through the Jak-STAT signaling pathway." (PMID 37089432, 2023).
neuroblastoma (12 papers, 2005 to 2025). Neuroblastoma (NB) is the most common solid, extracranial childhood tumor. "Expression of GFAP was reduced (nonsense versus shRNA CgA, 1.0±0.1 versus 0.02±0.01, P<0.05), whereas expression of PMP22 (1.0±0.02 versus 3.3±0.5, P<0.05) and SERPINF1 (1.0±0.1 versus 3.1±0.5, P<0.01) was increased in the shRNA CgA transfectants compared to nonsense control neuroblastoma cells." (PMID 30833285, 2019). "SERPINF1 may serve as a multifunctional antitumour agent in neuroblastomas, inhibiting angiogenesis." (PMID 15870709, 2005).
ovarian carcinoma (11 papers, 2016 to 2025). A malignant neoplasm originating from the surface ovarian epithelium. "However, many studies substantiated that SERPINF1 promotes the growth and metastasis of esophageal cancer, liver cancer, and ovarian cancer." (PMID 36980858, 2023).
myopia (10 papers, 2012 to 2024). "A decrease in SERPINF1 was associated with neovascularization and high myopia." (PMID 33217969, 2020). "Considering the ubiquity of the serpin proteins in the human system and their functional relevance in the pathogenesis of many ‘serpinopathies’ when deficient, it is therefore no surprise that previous studies of the human AH have shown significant decrement of SERPINF1 in patients with high myopia." (PMID 28273097, 2017).
cervical cancer (8 papers, 2016 to 2025). A primary or metastatic malignant neoplasm involving the cervix. "The present study suggests that TXNDC5 is a susceptibility gene in cervical cancer, and high expression of this gene contributes to abnormal angiogenesis, vasculogenic mimicry and metastasis by down-regulating SERPINF1 and TRAF1 expression." (PMID 29207620, 2017). "In cancerous diseases, SERPINF1 functions as a tumor suppressor in cervical cancer, which is downregulated by TXNDC5, resulting in stimulating cell migration, vasculogenic mimicry and angiogenesis." (PMID 32595417, 2020). "SERPINF1 inhibits angiogenesis and metastasis, induces tumor cell apoptosis and differentiation, and activates cellular immunity against cervical cancer." (PMID 29207620, 2017).
liver fibrosis (8 papers, 2014 to 2025). "SERPINF1 prevents liver fibrosis and hepatic stellate cell activation by down-regulating the expression of PDGF receptor-α/β and blocking the phosphorylation of Akt and ERK induced by PDGF, which plays an important role in hepatic stellate cell activation." (PMID 36267567, 2022). "These facts suggest that SERPINF1 may be a marker of hepatic fibrosis." (PMID 36267567, 2022). "The beneficial effects of hepatokines include 1) improvement of insulin sensitivity (FGF21); 2) prevention of liver fibrosis (FGF21, HMGB1, PST, AHSG and SERPINF1) and 3) reduction of inflammation and lipid accumulation (FGF21, HMGB1 and LECT2)." (PMID 36267567, 2022).
depression (7 papers, 2017 to 2025). "The present study showed that multiple pontine genes, including Anxa1, Serpinf1, Arrb1, Cplx2, Nrg1, and Psen1 were altered in a model of depression." (PMID 39135796, 2024). "This study showed that SNS improved the downregulation of Serpinf1 expression in a rat model of depression, which may be an antidepressant mechanism of SNS." (PMID 39135796, 2024).
colon carcinoma (6 papers, 2011 to 2024). "Another molecule associated with colon carcinoma is SERPINF1." (PMID 39758846, 2024).
psoriasis (6 papers, 2020 to 2025). An autoimmune condition characterized by red, well-delineated plaques with silvery scales that are usually on the extensor surfaces and scalp. "On the contrary, in psoriasis, more inflammation-related spatially variable genes (e.g. SERPINF1, FKBP5, IFIT1/3, DDX58) were identified." (PMID 38433843, 2024).
glioblastoma (5 papers, 2015 to 2025). The most malignant astrocytic tumor (WHO grade IV). "For example, the Sncg cell type has been reported in neurotic pathology of multiple system atrophy, the Serpinf1 is downregulated in primary malignant brain tumor (i.e. glioblastoma) and the Astro deletion reduces the brain edema." (PMID 39758128, 2025). "These discovered cell types are very informative biomarkers for several brain diseases including multiple system atrophy (Sncg), glioblastoma (Serpinf1) and brain edema (Astro)." (PMID 39758128, 2025). "While these rare cells only occupy very minor proportions (e.g. 0.09%), they are key biomarkers for several brain diseases including multiple system atrophy (Sncg), glioblastoma (Serpinf1) and brain edema (Astro)." (PMID 39758128, 2025).
Stroke (5 papers, 2014 to 2022). Sudden impairment of blood flow to a part of the brain due to occlusion or rupture of an artery to the brain. "For example, protein levels of SERPINF1 showed MR evidence to support a putative causal effect on stroke in African ancestry (p = 3.76 × 10−5) but showed little evidence of an effect in European ancestry (p = 0.83) (the full results could be queried using the EpiGraphDB web application)." (PMID 36388766, 2022). "Eight protein-disease pairs were ranked as the most valuable findings after the filtering, which include IL-7R and TNFSF12 level on asthma; ACE level on COPD; AIF1 level on HF; SERPINF1 level on stroke; and SERPINE2, F11, KLKB1, and ABO level on VTE." (PMID 36388766, 2022). "Three of the 16 observational associations passed FDR < 0.05 in this analysis, which included ACE level on COPD, AIF1 level on HF, and SERPINF1 on stroke." (PMID 36388766, 2022).
Hypertension (4 papers, 2013 to 2025). The presence of chronic increased pressure in the systemic arterial system. "These correspond to LRP5 (which encodes Low Density Lipoprotein Receptor-Related Protein 5) and SERPINF1 (which encodes Pigment Epithelium Derived Factor (PEDF) belonging to Serpin Peptidase Inhibitors superfamily) respectively; and both contribute to hypertension." (PMID 29420653, 2018).
metastatic tumors (4 papers, 2011 to 2022). "We also found that SERPINF1 expression was significantly higher in stage III/IV disease than in stage I/II disease, consistent with the notion that PEDF promotes metastatic disease." (PMID 36056141, 2022). "We further assessed whether SERPINF1 expression was higher in metastatic tumors than in primary tumors using an RNA-sequencing dataset (GSE137237) which are consisted of 11 matched pairs of tumors." (PMID 36056141, 2022).
asthma (3 papers, 2021 to 2023). "Two of the pairs, SERPINF1 on asthma and KLKB1 on VTE, were not reported in any of the pQTL studies and are not under clinical investigation yet, which we have therefore suggested are completely novel protein-disease pairs identified in this study." (PMID 36388766, 2022).
emphysema (3 papers, 2009 to 2024). "Gene expression profiling of lung from emphysema patients identified seven candidate genes associated with emphysema severity including COL6A3, SERPINF1, ZNHIT6, NEDD4, CDKN2A, NRN1 and GSTM3." (PMID 19723343, 2009). "SERPINF1 and ISM1 protect against emphysema formation, whereas AQP1 promotes eosinophilic infiltration." (PMID 38203236, 2023). "Regarding the genes regulating angiogenesis, SERPINF1 and ISM1 upregulation protect against emphysema formation, whereas AQP1 upregulation promotes eosinophil infiltration." (PMID 38203236, 2023). "The candidate genes (CDKN2A, GSTM3, COL6A3, SERPINF1, NRN1, NEDD4 and ZNHIT6) had ontologies that were relevant to emphysema progression, including cell cycle regulation (CDKN2A), collagen (COL6A3), anti-angiogenesis (SERPINF1) and oxidative stress (GSTM3)." (PMID 19723343, 2009). "In conclusion, we have used microarray technology to identify seven plausible candidate genes with potential involvement in the progression from mild to moderate emphysema, two of which, COL6A3 and SERPINF1, are concordantly increased in three different studies." (PMID 19723343, 2009).
gastric cancer (3 papers, 2022 to 2024). A primary or metastatic malignant neoplasm involving the stomach. "High expression of SERPINF1 was detected in gastric cancer patients with poor prognosis and was correlated with immune cell infiltration." (PMID 37333017, 2023). "The analysis of various gastric cancer cell lines and gastric cancer patient samples also revealed a positive association between ELK3 and BMP1, LOXL2, SNAI1, SERPINF1, DCN, and NID1, and these genes were associated with a poor prognosis." (PMID 35409069, 2022). "OSMR, LRP6, and SERPINF1 were expressed in most gastric cancer samples." (PMID 37333017, 2023). "It is reported that SERPINF1 is involved in the migration and invasion of ECM remodeling in gastric cancer." (PMID 39221148, 2024). "Patients with gastric cancer with a high expression of BMP1, LOXL2, SNAI1, SERPINF1, DCN, and NID1 had a poor prognosis." (PMID 35409069, 2022). "The gene analysis of samples from patients with gastric cancer indicated that a high ELK3 expression is positively correlated with BMP1, LOXL2, SNAI1, SERPINF1, DCN, and NID1 expression, all of which are closely associated with a poor prognosis." (PMID 35409069, 2022). "First, the correlation between ELK3 expression and BMP1, LOXL2, SNAI1, SERPINF1, DCN, and NID1 expression was analyzed in 19 different gastric cancer cell lines." (PMID 35409069, 2022). "Co-expression of stromal SERPINF1 and tumor cell LRP6, which is one of the ligand–receptor interactions of M2 macrophages and tumor cells, was correlated with lymph node metastasis in gastric cancer samples." (PMID 37333017, 2023). "Notably, the analysis of patients with gastric cancer indicated the marked positive regulation of ELK3 and BMP1, LOXL2, SNAI1, SERPINF1, DCN, and NID1 gene expression, suggesting a significant positive correlation between ELK3 and ECM remodeling-associated genes in gastric cancer." (PMID 35409069, 2022). "The ELK3 expression in gastric cancer cells and human gastric cancer samples positively correlated with that of BMP1, LOXL2, SNAI1, SERPINF1, DCN, and NID1, suggesting that this gene signature may be predictive molecular markers for aggressive gastric cancer progression." (PMID 35409069, 2022). "The interaction between SERPINF1 and LRP6 has not been reported in gastric cancer." (PMID 37333017, 2023).
osteoporosis (3 papers, 2014 to 2023). A condition of reduced bone mass, with decreased cortical thickness and a decrease in the number and size of the trabeculae of cancellous bone (but normal chemical composition), resulting in increased fracture incidence. "In conclusion, SERPINF1 variants cause a mineralization defect resulting in an OI, with a combination of congenital osteoporosis and osteomalacia caused by increased osteoclast activity, which forms 12.5 % of our patients." (PMID 37425194, 2023).